LMF1 (lipase maturation factor 1)
Description:
Involved in the maturation of specific proteins in the endoplasmic reticulum. Required for maturation and transport of active lipoprotein lipase (LPL) through the secretory pathway. Each LMF1 molecule chaperones 50 or more molecules of LPL.
Synonyms: C16orf26; TMEM112; HMFN1876; JFP11; FLJ12681; FLJ22302; TMEM112A
Tractability: Antibody: UniProt predicts a signal peptide or a membrane-spanning region.
Gene: Protein-coding gene on chromosome 16 (853,634 to 981,318, reverse strand). Ensembl gene ENSG00000103227.
Subcellular location: Endoplasmic reticulum membrane
Pathways (Reactome):
Transport of small molecules: Assembly of active LPL and LIPC lipase complexes
Gene Ontology:
Biological process: triglyceride metabolic process; protein maturation
Cellular component: endoplasmic reticulum membrane
Genetic constraint (gnomAD): Loss-of-function variants: 68 observed, 57.94 expected, observed/expected ratio (o/e) 1.17, 90% interval 0.96 to 1.44. The synonymous counts are far from expectation, so gnomAD's model fits this gene poorly and the ratio says little. Missense variants: 948 observed, 756.08 expected, observed/expected ratio (o/e) 1.25, 90% interval 1.19 to 1.32. Synonymous variants: 418 observed, 316.07 expected, observed/expected ratio (o/e) 1.32, 90% interval 1.22 to 1.43.
Homologues: Orthologues: chimpanzee LMF1 (95% identical), macaque LMF1 (89% identical), rat Lmf1 (81% identical), mouse Lmf1 (78% identical), pig LMF1 (77% identical), guinea pig LMF1 (77% identical), tropical clawed frog lmf1 (68% identical), zebrafish lmf1 (58% identical), dog LMF1 (46% identical), Caenorhabditis elegans K11G12.6 (23% identical). Paralogues in human: LMF2 (30% identical).
Diseases named in the same sentence as LMF1 in open-access papers:
LMF1 is named in the same sentence as 32 diseases in open-access papers, as found by Europe PMC text mining. Sharing a sentence is not in itself a finding about the gene and the disease. The quoted sentences say what the papers report.
hypertriglyceridemia (34 papers, 2009 to 2025). A laboratory test result indicating elevated triglyceride concentration in the blood. "This study reports a case of a 33-year-old Ecuadorian mestizo woman presenting with recurrent pancreatitis secondary to severe hypertriglyceridemia, in whom two LMF1 variants of uncertain significance (VUS) were identified." (PMID 40142634, 2025). "Genetic studies identified a heterozygous mutation in the LMF1 gene, suggesting a rare form of hypertriglyceridemia related to LMF1." (PMID 40142634, 2025). "Mutations in LMF1 represent an exceptionally rare cause of severe hypertriglyceridemia, and identifying these cases through genetic studies is crucial for appropriate clinical management." (PMID 40142634, 2025). "Some cases of severe hypertriglyceridemia have been suggested to have a digenic origin, involving mutations in both LMF1 and LPL." (PMID 40142634, 2025). "Due to the low prevalence of such cases, clinical reports of severe hypertriglyceridemia caused by LMF1 mutations remain extremely limited." (PMID 40142634, 2025). "Our NGS analysis revealed 10 rare variants at 4 genes (APOA1, APOA4, APOC2, and LMF1) related to hypertriglyceridemia." (PMID 35999587, 2022). "Our study underscores the complexity of hypertriglyceridemia and the need for the combination of extensive molecular genetic testing and clinical characterization; in addition, expands the spectrum of LMF1 mutations." (PMID 35368694, 2022). "Both the clinical and in vitro data suggest that severe hypertriglyceridemia was of digenic origin caused by LMF1 and LPL mutation double heterozygosity in this patient." (PMID 35368694, 2022). "Lipase maturation factor 1 (LMF1) is a profound regulator of plasma lipid metabolism and majority studies mainly focused on mutations of LMF1 determining severe hypertriglyceridemia." (PMID 31442207, 2019). "Hypertriglyceridemia in LMF1-/- pups was due to combined lipase deficiency as demonstrated by dramatically reduced post-heparin LPL and HL activities." (PMID 25302068, 2014). "Our results demonstrate that whereas LMF1 is dispensable for the viability of mouse embryo, LMF1 deficiency is associated with lipase deficiency, hypertriglyceridemia and neonatal lethality." (PMID 25302068, 2014). "Mutations in LMF1 are associated with lipase deficiency and severe hypertriglyceridemia indicating the critical role of LMF1 in plasma lipid homeostasis." (PMID 25302068, 2014). "Highlighting the critical role of LMF1 in lipase expression and lipid metabolism, patients with homozygous LMF1 mutations exhibit plasma lipase deficiency and hypertriglyceridemia." (PMID 25302068, 2014). "LMF1-/- progeny were born at Mendelian ratios and exhibited combined lipase deficiency, hypertriglyceridemia and neonatal lethality." (PMID 25302068, 2014). "A candidate variant in the LMF1 gene for hypertriglyceridemia has been identified." (PMID 39836076, 2025). "In 2012, we found an excessive prevalence of rare variants in LPL, APOC2, GPIHBP1, APOA5, and LMF1 in patients with severe hypertriglyceridemia, again indicating that heterozygosity was a predisposing factor for, although not an absolute cause of severe hypertriglyceridemia or MCM." (PMID 32793115, 2020). "Variants in the lipoprotein lipase (LPL), apolipoprotein C-II (APOC2), apolipoprotein A-V (APOA5), GPIHBP1 and LMF1 genes may cause severe hypertriglyceridemia (HTG), which is now the second-leading aetiology of acute pancreatitis in China." (PMID 29921298, 2018). "Importantly, mice with loss of function mutations in Lmf1 develop severe hypertriglyceridemia." (PMID 19825173, 2009). "This is a new Ecuadorian report of LMF1-related hypertriglyceridemia, highlighting the need for functional studies to confirm pathogenicity." (PMID 40142634, 2025). "Mutations in LMF1 are typically found in a homozygous or compound heterozygous state and lead to a deficiency in LPL activity, resulting in severe hypertriglyceridemia." (PMID 40142634, 2025).
hypertriglyceridemia (continued). "For severe hypertriglyceridemia, pathogenic variants in genes LPL, APOA5, APOC2, GPIHBP1, and LMF1, associated with hyperlipidemia should be considered." (PMID 36051701, 2022). "The most severe type of HTG is primary (or hereditary) hypertriglyceridemia, linked to pathogenic genetic variants in LPL, APOC2, LMF1, and APOA5 genes." (PMID 35741823, 2022). "Most variants interfering with triglyceride metabolism and causing hypertriglyceridemia are loss of function variants (LOF), and mainly found in the LPL, APOC2, APOA5, LMF1 and GPIHBP1 genes." (PMID 35237305, 2022). "The combination of LMF1 and LPL gene mutations significantly decreased LPL mass, which contributes to severe hypertriglyceridemia." (PMID 35368694, 2022). "A set of 53 single nucleotide polymorphisms (SNPs) previously associated with triglycerides levels, as well as 37 rare variants within the five main genes associated with hypertriglyceridemia (i.e. LPL, APOC2, APOA5, LMF1 and GPIHBP1) were analyzed." (PMID 33588820, 2021). "One such protein is the lipase maturation factor (LMF1), which is essential for LPL processing since loss-of-function variants in LMF1 cause hypertriglyceridemia due to inefficient LPL secretion." (PMID 34356847, 2021). "Variants on genes known to cause severe hypertriglyceridemia such as LPL, APOC2, GPIHBP1, APOA5, and LMF1 were first selected and interpreted." (PMID 32765589, 2020). "Severe hypertriglyceridemia (HTG) has been linked to defects in LPL, APOC2, APOA5, LMF1 and GBIHBP1 genes." (PMID 23151256, 2012). "Notably, genetic variations in LMF1 were significantly correlated with severe hypertriglyceridemia, especially among individuals with pancreatitis, who exhibited markedly elevated triglyceride levels." (PMID 40428368, 2025). "Severe hypertriglyceridemia, in the form of Familial Chylomicronaemia Syndrome (FCS), is a rare autosomal recessive disease caused by pathogenic variants especially in the LPL gene but also in APOC2, APOA5, LMF1 and GPIHBP1." (PMID 35237305, 2022). "In Mexico, hypertriglyceridemia constitutes a health problem in which the genetic bases have been scarcely explored; therefore, our objective was to describe biochemical–clinical characteristics and variants in the APOA5, GPIHBP1, LMF1, and LPL genes in patients with primary hypertriglyceridemia." (PMID 36613909, 2022). "The hypertriglyceridemia in cld mice suggested that the human ortholog LMF1 on chromosome 16 could be a candidate gene for regulating TG metabolism, and various LMF1 mutations have been identified in patients with hypertriglyceridemia." (PMID 32849290, 2020). "In addition to hypertriglyceridemia, plasma concentrations of total cholesterol are also elevated in LMF1-/- mice, a likely consequence of diminished catabolism and accumulation of chylomicron particles due to LPL deficiency." (PMID 25302068, 2014). "Indeed, LMF1-/- pups exhibit hypertriglyceridemia and severely diminished post-heparin LPL and HL activities, hallmark features of LMF1 deficiency in the cld mouse model." (PMID 25302068, 2014). "Besides LPL, there are other genes involved in primary hypertriglyceridemia phenotypes (most notably, APOC2, APOA5, LMF1, and GPIHBP1)." (PMID 36051701, 2022). "No mutation in the major genes involved in severe hypertriglyceridemia (LPL, APOAV, APOCII, LMF1, GPIHBP1) was found." (PMID 35011612, 2021). "Neonatal lethality in LMF1-/- mice is not unique among mouse models of hypertriglyceridemia." (PMID 25302068, 2014).
familial chylomicronemia syndrome (10 papers, 2020 to 2025). A rare autosomal recessive disease characterized by the buildup in the blood of fat particles called chylomicrons (chylomicronemia), severe hypertriglyceridemia, and the risk of recurrent and potentially fatal pancreatitis and other complications. "Mutations in different genes have been shown to cause monogenic dyslipidemia, including LDLRAP1 mutations that are involved in autosomal recessive hypercholesterolemia, ABCG5/ABCG8, involved in sitosterolemia, or LMF1, which is associated with familial chylomicronemia syndrome." (PMID 37887310, 2023). "When due to very rare monogenic mutations in the genes encoding the enzyme, lipoprotein lipase, or its regulators, APOC2, APOA5, GPIHBP1, and LMF1, it is referred to as the familial chylomicronemia syndrome." (PMID 33193106, 2020). "At the genetic level, severely elevated triglyceride levels resulting from familial chylomicronemia syndrome (FCS) are caused by homozygous or biallelic loss-of-function variants in LPL, APOC2, APOA5, LMF1, and GPIHBP1 genes." (PMID 32793115, 2020). "Familial chylomicronemia syndrome (FCS) is a rare disorder of triglyceride (TG) metabolism caused by loss of function variants in one of five known canonical genes involved in chylomicron lipolysis and clearance—LPL, APOC2, APOA5, LMF1, and GPIHBP1." (PMID 38974610, 2024). "This includes familial chylomicronemia syndrome (FCS), a condition caused by mutations in the lipoprotein lipase (LPL) gene or other genes that regulate the function of this enzyme (i.e APOC2 and the LMF1 (lipase maturation factor 1))." (PMID 33588820, 2021). "Furthermore, three patients had variants linked to familial chylomicronemia syndrome: one was compound heterozygous for two likely pathogenic variants in LPL, another was homozygous for a likely pathogenic variant in LMF1, and the third was heterozygous for a likely pathogenic variant in LPL." (PMID 40806502, 2025).
pancreatitis (6 papers, 2015 to 2025). Inflammation of the pancreas. "FCS due to biallelic LPL, APOC2, GPIHBP1, or LMF1 variants accounted for <5% of cases and showed extreme TG elevations (>2800 mg/dL) with pancreatitis prevalence (>70%)." (PMID 41300829, 2025). "Carriers of APOA5, GPIHBP1, or LMF1 variants exhibited intermediate TG levels (1800–2500 mg/dL) and substantial pancreatitis risk, whereas APOB and APOC3 variant carriers had milder TG elevations (500–1500 mg/dL) but were more frequently associated with hepatic steatosis and metabolic comorbidities." (PMID 41300829, 2025).
dyslipidemia (5 papers, 2014 to 2025). "In conclusion, we validated a new LMF1-deficient mouse model by demonstrating that it recapitulates salient phenotypes of cld mutant mice including neonatal lethality, dyslipidemia and combined lipase deficiency." (PMID 25302068, 2014).
hyperlipidemia (4 papers, 2014 to 2022). "Four representational genes, including Apolipoprotein B gene (APOB), Carboxylesterase 1 gene (CES1), Delta Like Non-Canonical Notch Ligand 1 gene (DLK1), Lipase Maturation Factor 1, (LMF1), were contributed to hyperlipidemia." (PMID 27888796, 2016). "Two patients with other five family members were included in this study for DNA-sequences of hyperlipidemia-related genes (such as LPL, APOC2, APOA5, LMF1, and GPIHBP1) and 43 healthy individuals and 70 HTG subjects were included for the screening of LPL gene mutations." (PMID 24646025, 2014).
acute pancreatitis (3 papers, 2018 to 2023). An acute inflammatory process that leads to necrosis of the pancreatic parenchyma. "Chinese patients with HTG-associated acute pancreatitis (HTG-AP) were screened for rare nonsense, frameshift, missense or canonical GT-AG splice site variants in LPL and four other lipid metabolism-related genes (APOC2, APOA5, GPIHBP1 and LMF1) by Sanger sequencing." (PMID 37550668, 2023).
Obesity (3 papers, 2019 to 2022). Accumulation of substantial excess body fat. "This is the first time that a heterozygous LMF1 nonsense variant was found in a HTG-AP patient with severe obesity and heavy smoking, highlighting an important interplay between genetic and lifestyle factors in the etiology of HTG." (PMID 30885219, 2019). "In conclusion, we have for the first time discovered a novel and heterozygous LMF1 nonsense variant in a HTG-AP patient with severe obesity and heavy smoking, highlighting an important interplay between genetic and lifestyle factors in the etiology of HTG." (PMID 30885219, 2019).
glioma (2 papers, 2022 to 2024). A benign or malignant brain and spinal cord tumor that arises from glial cells (astrocytes, oligodendrocytes, ependymal cells). "In addition, MR analysis revealed that the causal effect is specifically distinct among glioma subtypes, notably distinguishing GBM from non‐GBM, given their shared sole causal gene, LMF1." (PMID 39722126, 2024). "A GWAS in glioma in European populations found LMF1 (rs3751667) at 16p3.3 to be involved in LGG." (PMID 35887658, 2022).
atherosclerosis (1 paper, 2020). A disease characterized by the build-up of fatty material and calcium deposition in the arterial wall resulting in partial or complete occlusion of the arterial lumen. "One would predict that LMF1 loss-of-function mutations would have effects on atherosclerosis surpassing those of LPL-deficiency because LMF1 is also needed for maturation of HL and EL." (PMID 32849290, 2020). "The effect of LMF1 on atherosclerosis in mouse models is unknown." (PMID 32849290, 2020).
brain neoplasm (1 paper, 2022). A neoplasm (disease) that involves the brain. "However, RBFOX1 (rs8044700) near LMF1 in our TPMI study has an alternative splicing function to modify brain neoplasms and tend to be associated with malignancy." (PMID 35887658, 2022). "In addition to our novel SNP rs3751667 of LMF1, the gene is associated with the malignant brain neoplasm profile in TPMI GWAS." (PMID 35887658, 2022). "Thus, LMF1 in the Han Chinese population is predominantly related to malignant neoplasms of the brain and might predispose an individual toward brain cancer by regulating ER stress." (PMID 35887658, 2022). "For the PPI network, primarily signals in the malignant brain neoplasm associated with DPP6, RBFOX1, LMF1, and EDARADD to present regulation of alternative splicing of RNA by APP6 and RBFOX1, maturation of specific proteins in ER by LMF1, and activation of NF-κB through EDARADD." (PMID 35887658, 2022).
cardiomyopathy (1 paper, 2026). A disease of the heart muscle or myocardium proper. "These include known Mendelian cardiomyopathy risk genes such as FLNC and ACTN2, and novel regulatory candidates like CAMK2D, LMF1, MYOZ1, SKI, SYNPO2L, and TKT." (PMID 41646816, 2026).
Hypercholesterolemia (1 paper, 2022). An increased concentration of cholesterol in the blood. "The proband’s mother, who carried the LMF1 gene mutation, had TG values in the normal range but presented with hypercholesterolemia." (PMID 35368694, 2022).
preeclampsia (1 paper, 2022). Preeclampsia is a hypertensive disorder of pregnancy that is characterized by new-onset hypertension with proteinuria presenting after 20 weeks of gestation, and depending on mild or severe forms may initially present with severe headache, visual disturbances, and hyperreflexia. "The aberrant copies of APOBEC3A, APOBEC3A_B, BTNL3, and LMF1 between preeclampsia patients and controls were verified by quantitative polymerase chain reaction." (PMID 35651912, 2022).
Stroke (1 paper, 2023). Sudden impairment of blood flow to a part of the brain due to occlusion or rupture of an artery to the brain. "Our bioinformatics analysis results indicated that the expression levels of LIPC and its related genes (APOB, CETP, PNPLA2, and LMF1) showed significant differences between stroke and control groups." (PMID 37273686, 2023). "Based on the Gene Expression Omnibus (GEO) database analysis, significant differences in the expression levels of LIPC, APOB, CETP, PNPLA2, and LMF1 between the control and stroke groups were observed." (PMID 37273686, 2023). "Furthermore, bioinformatics analysis results demonstrated that the expression levels of LIPC and its related genes (APOB, CETP, PNPLA2, and LMF1) were significantly different between the control and stroke groups (p < 0.05), and LIPC-related proteins were mainly related to lipid metabolism." (PMID 37273686, 2023).
cancer (2 papers, 2022 to 2023). A tumor composed of atypical neoplastic, often pleomorphic cells that invade other tissues. "The 16p13.3 association with malignant neoplasm that is marked by rs3751667 maps to 5_prime_UTR of LMF1, the encoded product of which belongs to an integral component of the membrane that is predicted to be active in the endoplasmic reticulum (ER) membrane." (PMID 35887658, 2022). "Seven SNPs at the LMF1 locus showed significant associations with malignant neoplasms." (PMID 35887658, 2022). "There are seven SNPs at the LMF1 locus with significant associations with malignant neoplasms." (PMID 35887658, 2022). "A total of 20 target mRNAs of three miRNAs were predicted, among which seven target mRNAs—ASAP3, BCL2L2, LMF1, PPM1L, PTPN21, SLC18A2, and NR3C2—had prognostic value; PRKACB, PDCD4, RPS6KA5, and BCL2L2 were enriched in the miRNA cancer pathway." (PMID 36829221, 2023). "Among these mRNAs, the prognostic values and mechanisms of LMF1, PPM1L, and PTPN21 have rarely been reported in cancers." (PMID 36829221, 2023).
LMF1 also shares sentences with these, for which no sentence is quoted: Hyperglycemia (2 papers); lipodystrophies (2); Autoimmunity (1); autosomal recessive disease (1); central obesity (1); chronic renal failure (1); coronary artery disease (1); diabetes (1); familial chylomicronemia (1); Hepatic steatosis (1); hepatoma (1); hereditary pancreatitis (1); Hypertension (1); metabolic disorder (1); sitosterolemia (1); steatosis (1); tumour (1).